VCAM1 (vascular cell adhesion molecule 1)
Diseases named in the same sentence as VCAM1 in open-access papers (continued):
Sharing a sentence is not in itself a finding about the gene and the disease.
endothelial dysfunction (continued). "We demonstrated that HCV co-infection and deficiency of effective cART are linked with higher serum concentrations of VCAM-1 being a biomarker of endothelial dysfunction." (PMID 35159966, 2022). "It was reported that higher levels of ICAM-1 and VCAM-1, two adhesion molecules, were associated with impaired endothelial dysfunction in active AS." (PMID 34259096, 2021). "In this study, we demonstrate that ponatinib causes dose-dependent endothelial dysfunction, in terms of reduced angiogenic activity and increased expression of VCAM-1, one of the mediators that play a key role in the early stages of atherogenesis." (PMID 32197359, 2020). "Cytokine IL-6 is involved in the development of endothelial dysfunction by regulating the expression of the VCAM1 and ICAM1 genes, encoding intercellular adhesion molecules." (PMID 33659786, 2020). "In particular, we investigated VCAM-1, an important pro-inflammatory marker that has been implicated in endothelial dysfunction and early stages of atherogenesis." (PMID 28253885, 2017). "IL-6 has been linked with CV disease and, together with VCAM-1, has been implicated in in-vitro and animal models of endothelial dysfunction in uraemia." (PMID 28829810, 2017). "Our previous cell culture study using a static HDMEC model documented a dose dependent up-regulation of pro-atherogenic adhesion molecules (ICAM-1, VCAM-1), which are associated with the endothelial dysfunction." (PMID 23514369, 2013). "The same polymorphism also modulates the association between PM and inflammation and endothelial dysfunction, as adhesion molecules, vascular cell adhesion molecule-1 (VCAM-1) and intercellular adhesion molecule-1 (ICAM-1) were particularly higher in subjects carrying the GSTM1 null gene." (PMID 40427454, 2025). "As VCAM-1 has been directly implicated in endothelial dysfunction of the blood–brain barrier, a similar role for the protein in disrupting the gut-blood barrier could be plausibly linked to the “leaky gut” physiology commonly observed in IBD patients." (PMID 40095109, 2025). "Vascular cell adhesion molecule-1 (VCAM-1), an endothelial serum biomarker using enzyme-linked immunosorbent assay (ELISA), is indicative of vascular inflammation and can be linked to endothelial dysfunction, serving as a link between CSVD and its causative effects rather than a diagnostic tool." (PMID 39963633, 2025). "These confirm causal contribution of PAA to endothelial dysfunction through VCAM1 modulation." (PMID 40355758, 2025). "Biomarkers like sICAM-1 and VCAM-1 indicate endothelial dysfunction and thrombotic risk." (PMID 40299499, 2025). "LPS treatment activates the TLR4/NFκB signaling pathway, leading to the upregulation of pro-inflammatory genes such as IL-6 and VCAM-1, which are key mediators of vascular inflammation and endothelial dysfunction commonly associated with obesity and cardiovascular disease." (PMID 41010478, 2025). "Elevated levels of circulating Vcam1 are associated with endothelial dysfunction." (PMID 39337408, 2024). "Among these markers, C-reactive protein (CRP), monocyte chemoattractant protein-1 (MCP-1), intercellular adhesion molecule-1 (ICAM-1), and vascular cell adhesion protein 1 (VCAM-1) have all been implicated in endothelial dysfunction and the development of vascular disease." (PMID 37570877, 2023). "Here, we examined whether treatment with ET-1 antagonists BQ123/BQ788 or insulin (1 mU/mL and 10 mU/mL doses can reduce markers associated with endothelial dysfunction ET-1, VCAM1 and ICAM1." (PMID 37893034, 2023). "The association between VCAM-1 and endothelial dysfunction was mediated by iPTH as well." (PMID 35903313, 2022). "In humans, recent studies suggest that resistin directly causes endothelial dysfunction by increasing endotelin-1 (ET-1) secretion as well as vascular cell adhesion protein 1 (VCAM1) and monocyte chemoattractant protein-1 (MCP-1) and by reducing the nitric oxide synthetase." (PMID 35011183, 2021).
endothelial dysfunction (continued). "Fish long-chain omega-3 PUFA helped to protect against vascular risk factors such as inflammation, endothelial dysfunction (with reduced circulating markers such as VCAM-1, E-selectin, and ICAM-1), and vascular resistance (i.e., improve flow-mediated arterial dilation)." (PMID 33718454, 2021). "Seven biomarkers indicating endothelial dysfunction (mid‐regional proadrenomedullin (MR‐ProADM), syndecan 1, thrombomodulin, angiopoietin 2, endothelial cell‐specific molecule 1, vascular cell adhesion molecule 1 and E‐selectin) had stronger associations with sepsis than infection alone." (PMID 32073224, 2020). "Because endothelial dysfunction is associated with the expression of various cytoadhesins or selectins together with the production of proinflammatory chemokines, we investigated the impact of thrombin-induced endothelial senescence on VCAM-1 expression." (PMID 31581517, 2019). "Higher levels of ICAM-1, VCAM-1 and E-Selectin might be very useful in predicting patients at high risk of endothelial dysfunction, especially in the case of SCD patients with VOC, in this study." (PMID 29690499, 2018). "In the Coronary Artery Risk Development in Young Adults (CARDIA) Study, endothelial dysfunction was measured by circulating CAMs, namely sICAM-1, VCAM-1, P-selectin, E-selectin, and fractalkine in calendar years 1992–1993 and 2000–2001, whereas cognitive test scores were obtained during 2010–2011." (PMID 28596958, 2017). "Furthermore, 5-MTP reduced endothelial loss and detachment, ICAM-1 and VCAM-1 expressions, and inflammatory cell infiltration in the ligated arterial wall, suggesting attenuation of endothelial dysfunction." (PMID 27146795, 2016). "Within a longitudinal study we for the first time show that inflammation as measured by IL-6 and a biomarkers-based inflammation score and endothelial dysfunction as measured by VCAM-1, is associated with LVMI worsening over time in patients across the whole spectrum of pre-dialysis CKD." (PMID 26398099, 2015). "The increase in SREBP-1 activity and IL-1β production in lesions is associated with vascular inflammation and endothelial dysfunction in atherosclerotic pig aorta, as demonstrated by the induction of NF-κB, VCAM-1, iNOS, and COX-2, as well as by the repression of eNOS." (PMID 23825667, 2013). "However, severe inflammation in COVID-19 patients is believed to be correlated with endothelial dysfunction, as seen in higher levels of thrombomodulin and sVCAM-1 (soluble vascular cell adhesion molecule-1), which is the only independent biomarker associated with mortality." (PMID 36014561, 2022). "Interestingly, VCAM-1 has also been implicated as a mediator of endothelial dysfunction in obesity." (PMID 31037360, 2019). "The anti-inflammatory effects of polygodial are varied, including the inhibition of Intercellular adhesion molecule 1 (ICAM1) and Vascular cell adhesion molecule 1 (VCAM1), which are involved in endothelial dysfunction." (PMID 40286191, 2025). "The expression of endothelial dysfunction markers VCAM1, MMP9, and NOX1 in the lactate-treated group was significantly elevated, as indicated by the RT-qPCR." (PMID 41213933, 2025). "This study highlights the interplay between atherogenic status (e.g., elevated LDL-C), systemic inflammation (e.g., IL-6, hs-CRP), and coagulation-related endothelial dysfunction (e.g., sCD40-L, VCAM-1), which collectively contribute to CMVO pathogenesis." (PMID 40988197, 2025). "Endothelial dysfunction markers (VCAM-1, ICAM-1, sICAM-1/sVCAM-1),platelet activation (P-selectin), clotting factors (D-dimer, fibrinogen),hs-CRP (chronic inflammation), homocysteine (vascular stress marker)." (PMID 41031540, 2025). "First, spontaneous hypertensive rat models show reduced NO levels, elevated ET-1, inflammatory markers (e.g., IL-1β, TNF-α, MCP-1, VCAM-1), and ROS, indicating endothelial dysfunction, inflammation, and oxidative stress." (PMID 40230380, 2025).
endothelial dysfunction (continued). "TNF-α, by activating NF-κB signalling, increasing ROS production and up-regulating adhesion molecules, including ICAM-1 (Intercellular Adhesion Molecule-1) and VCAM-1 (Vascular Cell Adhesion Molecule-1), induces endothelial dysfunction." (PMID 41301783, 2025). "The degree of endothelial dysfunction can also be assessed by measuring the serum levels of molecules involved in this process, such as VCAM-1 (vascular cell adhesion molecule 1), ICAM-1, and ELAM-1 (endothelial leukocyte adhesion molecule 1/selectin)." (PMID 41010664, 2025). "The increase in soluble forms of adhesion molecules, ICAM-1 and VCAM-1, is an indicator of immune system activation and endothelial dysfunction." (PMID 40217768, 2025). "Induces pro-inflammatory signaling in endothelial cells, upregulates adhesion molecules (ICAM-1, VCAM-1), and decreases NO production, worsening endothelial dysfunction." (PMID 40529825, 2025). "Plasma levels of the markers of endothelial dysfunction angiopoietin-2, syndecan-1, and Vascular cell adhesion molecule 1 (VCAM-1) show a moderate positive correlation with PD-1 expression in CD4+ T-cells (shown for TP2)." (PMID 40595657, 2025). "These substances, in turn, stimulate the production of endothelial CCL2, ICAM-1, and VCAM-1, which exacerbate endothelial dysfunction." (PMID 40943241, 2025). "Sterile inflammation, caused by endothelial injury, leads to endothelial dysfunction via cytokines (IL-6, TNF-α, CRP) and the activation of NF-κB, increasing adhesion molecule (VCAM-1, ICAM-1, E-selectin) expression." (PMID 40299499, 2025). "Elevated Ang II promotes macrophage infiltration and stimulates excessive production of pro-inflammatory cytokines (e.g., IL-6, MCP-1) and adhesion molecules (e.g., VCAM-1), ultimately contributing to endothelial dysfunction." (PMID 41012594, 2025). "As such, concentrated regions of aberrant VCAM-1 overexpression generally delineate areas of endothelial dysfunction and disease activity in experimental disease models and human IBD patients." (PMID 40095109, 2025). "RT-qPCR demonstrated that SERPINE1 knockdown significantly downregulated endothelial dysfunction markers, including VCAM1, MMP9, and NOX1." (PMID 41213933, 2025). "We confirmed successful induction of endothelial dysfunction by confirming the upregulation of VCAM1 (P = 0.0031 at 10 ng/mL TNFα), ET-1 (P = 0.0034 at 10 ng/mL TNFα) and ICAM1 (P = 0.0014 at 10 ng/mL TNFα)." (PMID 40234537, 2025). "Similar to what we observed for PD-1, the frequencies of CD4+/CD8+ T-cells expressing these inhibitory receptors correlate positively with endothelial dysfunction and severity-related plasma markers (syndecan-1, VCAM-1, and ferritin)." (PMID 40595657, 2025). "Our data show that exposure to DEPs increased the concentrations of ICAM-1, VCAM-1, E-selectin and P-selectin in the plasma, and that nerolidol administration effectively prevented the rise in these markers of endothelial dysfunction." (PMID 40149705, 2025). "VCAM-1 is an endothelial adhesion molecule that plays a crucial role in vascular inflammation, immune cell recruitment, and endothelial dysfunction." (PMID 40385768, 2025). "Elevated levels of soluble ICAM-1 (sICAM-1) and soluble VCAM-1 (sVCAM-1) have been identified as biomarkers of endothelial dysfunction." (PMID 40299499, 2025). "After alcohol cessation Lyve1 and Stab2 expression returned to control levels, but in contrast, Icam1, Vcam1, and Cd34 stayed elevated or further increased suggesting that endothelial dysfunction persists after alcohol cessation." (PMID 40288442, 2025). "Compared to IL-6 and TNF-α, which primarily indicate systemic inflammation, VCAM-1 is a more specific marker of endothelial dysfunction." (PMID 40385768, 2025). "VCAM-1 is a marker of endothelial dysfunction and is upregulated in murine TB and pulmonary hypertension." (PMID 40126327, 2025).
endothelial dysfunction (continued). "This cascade promotes the expression of VCAM-1, facilitating leukocyte adhesion and promoting endothelial dysfunction." (PMID 40299499, 2025). "Severe hematotoxicity was linked to endothelial dysfunction, as evidenced by reduced levels of ANG1, soluble selectins, and increased soluble VCAM‐1 (sVCAM‐1) early after CAR‐T infusion." (PMID 41368079, 2025). "While VCAM-1 is minimally expressed on most resting vascular endothelial beds, it is significantly upregulated in areas of endothelial dysfunction following injury or stress." (PMID 40095109, 2025). "Evidence has also described higher concentrations of endothelial dysfunction markers decades postpartum, such as soluble vascular cell adhesion molecule-1, soluble E-selectin, sFlt-1, urinary albumin/creatinine ratio, and high-sensitivity C-reactive protein." (PMID 41375695, 2025). "Excessive activation of IFN pathways can drive endothelial dysfunction by inducing the expression of adhesion molecules and chemokines such as vascular cell adhesion molecule-1 (VCAM-1) and monocyte chemoattractant protein-1 (MCP-1)." (PMID 41359111, 2025). "The elevated levels of VEGFR2, ICAM-1, VCAM-1, and other less common vascular-related molecules further support the involvement of endothelial dysfunction and vascular activation in DME." (PMID 39685883, 2024). "It induces the expressions of ICAM-1 and VCAM-1, helps reduce the interaction among endothelial cells, and accelerates the progression of inflammation and endothelial dysfunction." (PMID 38195507, 2024). "Vascular Cell Adhesion Molecule-1 (VCAM-1) is critical in the pathophysiology of DN, serving as a mediator of inflammation and endothelial dysfunction." (PMID 39727989, 2024). "These markers include indicators of endothelial dysfunction (VCAM-1, ICAM-1, MCP-1) and an acute-phase reactant (CRP)." (PMID 39144845, 2024). "Treatment of HUtMEC cells with recombinant s(P)RR resulted in increased levels of endothelial dysfunction markers; VCAM-1, ICAM-1, and ET-1, suggesting that elevated s(P)RR has the potential to cause systemic maternal endothelial dysfunction." (PMID 38605139, 2024). "This in turn reduces the levels of endothelial dysfunction markers such as vascular cell adhesion molecule 1 (VCAM‐1), intercellular adhesion molecule 1 (ICAM‐1), and E‐selectin." (PMID 38405061, 2024). "Their concentrations, particularly VCAM-1, ICAM-1, and ESAM, have been shown to be associated with endothelial dysfunction, vascular damage, and increased risk of atherosclerotic cardiovascular disease." (PMID 39234240, 2024). "It should be noted that some of these molecules, such as VCAM-1 and E-selectin, are adhesion molecules involved in the interplay between endothelial dysfunction and inflammation." (PMID 38600563, 2024). "Another gene of particular interest is VCAM1, which facilitates the adhesion of leukocytes to endothelial cells, is involved in the inflammatory response, and is a biomarker of endothelial dysfunction." (PMID 38338971, 2024). "Soluble vascular cell adhesion molecule-1, a marker of endothelial dysfunction, is reported to correlate with the severity of hemolysis in patients with SCD-related PH." (PMID 38732015, 2024). "VCAM1 and ICAM1 are potential targets of biochanin A that are involved in AGE-RAGE signaling pathways and are associated with endothelial dysfunction." (PMID 38195507, 2024). "Increased endothelial expression of ICAM-1 and VCAM-1 was observed one-day post-ligation, and endothelial dysfunction was seen seven days post-ligation." (PMID 37174655, 2023). "In summary, increased TMAO levels, in animal models and human endothelial cells, contribute to increased adhesion of monocytes and low endothelial self-repair by the activation of PKC, NF-κB, and VCAM-1 signaling pathways, resulting in endothelial dysfunction." (PMID 37111261, 2023).
endothelial dysfunction (continued). "Several biomarkers have been associated with endothelial dysfunction in PAD, including adhesion molecules (intercellular adhesion molecule 1 [ICAM-1] and vascular cell adhesion protein 1 [VCAM-1]) and selectins (E-selectins and P-selectins)." (PMID 37446302, 2023). "Adhesion molecules such as intercellular adhesion molecule 1 (ICAM-1) and vascular cellular adhesion molecule 1 (VCAM-1) can be released into circulatory system when vasculature is damaged, accompanied by vascular inflammation and endothelial dysfunction." (PMID 36710676, 2023). "In order to characterize the inflammatory state and the endothelial dysfunction in our cohort of patients, we measured soluble Vascular Cell Adhesion Molecule-1 (sVCAM-1) and C-reactive protein (CRP) in their serum samples." (PMID 37398656, 2023). "Cardiac and pulmonary VCAM-1 expression was investigated as a general marker for endothelial dysfunction." (PMID 36717473, 2023). "Elevated levels of intercellular and vascular adhesion molecules (ICAM1, VCAM1), which are considered markers of endothelial dysfunction, have been observed in patients with CKD." (PMID 37109198, 2023). "The expression levels of ICAM-1, VCAM-1, vWF, and ET-1 in CiGEnCs were measured to evaluate the degree of endothelial dysfunction." (PMID 37188751, 2023). "Although several endothelial dysfunction markers were associated with LOF genotype, only Angpt-1 and VCAM-1 were independently associated after adjusting for age and complicated course." (PMID 36778250, 2023). "So, both ICAM-1 and VCAM-1 have been used as inflammation marker and endothelial dysfunction because the expression of both CAMs is enhanced by a variety of proatherogenic stimuli such as proinflammatory cytokines and reactive oxygen species." (PMID 37822716, 2023). "CER-001 infusion ameliorated systemic endothelial dysfunction by reducing VCAM-1 and ICAM-1 serum levels in both treated groups, with an increased effect of the two doses of ApoA-I complexes as emphasized at T6 time points." (PMID 37915050, 2023). "Current evidence suggests that concomitant administration of metformin during radiotherapy in rats decreases the expression of E-selectin, ICAM-1, and VCAM-1, thereby acting as a potent heart protector from endothelial dysfunction-induced damage." (PMID 35910360, 2022). "In human endothelial cells, quercetin or its metabolite isorhamnetin inhibit the expression of biomarkers of endothelial dysfunction including VCAM-1, ICAM-1 and MCP-1 at a physiologically attainable concentration of 2 μM." (PMID 35268723, 2022). "Increased serum ICAM-1 and VCAM-1 suggested increased cross talk between neutrophil and endothelial cell, as well as, endothelial dysfunction." (PMID 34449018, 2022). "The NET-dependent induction or aggravation of reduced eNOS phosphorylation and endothelial barrier integrity paralleled by increased plasma levels of soluble VCAM-1 suggest that NET contributes to endothelial dysfunction in DKD." (PMID 35889923, 2022). "Along the same line, high levels of markers of endothelial dysfunction such as vWF, P-selectin, and vascular cell adhesion protein (VCAM-1) are found in DVT patients." (PMID 35574486, 2022). "Upregulation of cellular adhesion molecules (ICAM-1 and VCAM-1), are among the phenotypic characteristics of endothelial dysfunction (VCAM-1)." (PMID 36408439, 2022). "As nephritis and renal damage occur due to direct podocyte injury and endothelial dysfunction and increase the expression of the vascular cell adhesion molecule 1 (VCAM-1)." (PMID 35631276, 2022). "After adjusting for eGFR, iPTH and VCAM-1 remained independent factors for predicting endothelial dysfunction measured using Ach-induced ILDF." (PMID 35903313, 2022). "The activated ACE2-Ang II axis can trigger macrophage infiltration and induce the secretion of several cytokines, including IL-6, CCL2, VCAM-1, and E-selectin, which induce endothelial dysfunction and, subsequently, coagulation." (PMID 35464491, 2022).